FN3K (fructosamine 3 kinase)
Description:
Fructosamine-3-kinase involved in protein deglycation by mediating phosphorylation of fructoselysine residues on glycated proteins, to generate fructoselysine-3 phosphate. Fructoselysine-3 phosphate adducts are unstable and decompose under physiological conditions. Involved in intracellular deglycation in erythrocytes. Involved in the response to oxidative stress by mediating deglycation of NFE2L2/NRF2, glycation impairing NFE2L2/NRF2 function (By similarity). Also able to phosphorylate psicosamines and ribulosamines.
Tractability: Small molecule: a structure with a bound ligand is known. PROTAC: ubiquitination databases record sites on it.
Target class: Enzyme; Transferase
Gene: Protein-coding gene on chromosome 17 (82,735,603 to 82,751,197, forward strand). Ensembl gene ENSG00000167363.
Subcellular location (Human Protein Atlas): Mitochondria
Pathways (Reactome):
Metabolism of proteins: Gamma carboxylation, hypusinylation, hydroxylation, and arylsulfatase activation
Gene Ontology:
Molecular function: protein-fructosamine 3-kinase activity; protein-ribulosamine 3-kinase activity; kinase activity
Biological process: epithelial cell differentiation; protein deglycation; fructosamine metabolic process; fructoselysine metabolic process; post-translational protein modification
Cellular component: mitochondrion; cytosol
Genetic constraint (gnomAD): Loss-of-function variants: 23 observed, 21.65 expected, observed/expected ratio (o/e) 1.06, 90% interval 0.76 to 1.5. The upper end of that interval is the gene's LOEUF score, 1.5, which puts it in group 6 of 6, group 1 being the genes least tolerant of losing a copy. Missense variants: 425 observed, 387.71 expected, observed/expected ratio (o/e) 1.1, 90% interval 1.01 to 1.19. Synonymous variants: 184 observed, 163.02 expected, observed/expected ratio (o/e) 1.13, 90% interval 1 to 1.27.
Homologues: Orthologues: chimpanzee FN3K (99% identical), macaque FN3K (98% identical), dog FN3K (90% identical), pig FN3K (90% identical), mouse Fn3k (89% identical), rabbit FN3K (88% identical), rat Fn3k (87% identical), guinea pig FN3K (86% identical), tropical clawed frog fn3k (57% identical), Caenorhabditis elegans Y116A8C.25 (34% identical). Paralogues in human: FN3KRP (64% identical).
Diseases named in the same sentence as FN3K in open-access papers:
FN3K is named in the same sentence as 20 diseases in open-access papers, as found by Europe PMC text mining. Sharing a sentence is not in itself a finding about the gene and the disease. The quoted sentences say what the papers report.
diabetes (9 papers, 2013 to 2025). "A regulatory axis between FN3K and glycated protein targets has been associated with conditions like diabetes and cancer." (PMID 39149269, 2024). "Regarding hypomethylated DMRs, they involved genes linked to metabolic control of diabetes such as FN3K, RPH3AL and HOX, HDAC4." (PMID 36870961, 2023). "A more recent study has identified two new mutations linked to T2DM and to female gender; furthermore, additional variants within FN3K gene are here reported adding new useful information to the possible role of FN3K in diabetes." (PMID 23573087, 2013). "Even if the role of FN3K in arterial hypertension remains unclear, polymorphisms of the FN3K gene in patients with diabetes display a protective role against severe microangiopathy and macroangiopathy diabetes complications." (PMID 35335911, 2022). "In this frame, fructosamine 3-kinase gene, located on chromosome 17q25.3 and organized in six exons, codes a 34 kDa protein expressed in every human tissue and whose greatest expression is in diabetes susceptible organs, such as kidney, heart, and nervous tissue." (PMID 23573087, 2013). "Similar to FN3K’s roles in the pathology of other diseases like diabetes, its phosphorylation activity is believed to be crucial for its regulation on NRF2." (PMID 39149269, 2024). "However, similar to FN3K’s roles in the pathology of other diseases like diabetes, its phosphorylation activity is believed to be crucial for its regulation of NRF2." (PMID 39843453, 2025). "Therefore, it would be interesting to see if a correlation between FN3K and GNEM could be found—as it exists, for example, in relation to diabetes mellitus." (PMID 36979358, 2023).
breast carcinoma (3 papers, 2021 to 2023). "But, brusatol is an Nrf2 inhibitor of natural origin significantly upregulated the FN3K expression in both BT-474 and T4-7D cells indicating the combinatorial implications of both FN3K and Nrf2 inhibitors in breast cancers by examining Nrf2-glycation patterns." (PMID 37910519, 2023). "Other anticancer drugs like platinum derivatives including cisplatin and oxaliplatin were also examined against their ability for modulating the FN3K expression in breast cancers after determining their cytotoxicity." (PMID 37910519, 2023). "This article is the main examination FN3K enzyme activity in human breast cancer growth, uncovering a critical relationship between enzymatic movement in tumor and pair-coordinated ordinary tissues." (PMID 35223406, 2021). "The present work intends to look into Glyoxalase1 (GLO1) and fructosamine-3-kinase (FN3K) activity in human breast carcinoma." (PMID 35223406, 2021). "The efficacy of these polyphenols must be determined in mediating FN3K-mediated deglycation for the development of NSMIs against breast cancer." (PMID 33466626, 2021). "Hence, the study concluded the potential implications of existing anticancer drugs to modulate FN3K activity in breast cancers." (PMID 37910519, 2023). "Therefore, the development of small molecule inhibitors is a significant strategy to inhibit selectively FN3K in breast cancers." (PMID 37910519, 2023). "Therefore, the targeted inhibition of FN3K using small molecule inhibitors is a viable strategy to inhibit breast cancer." (PMID 33466626, 2021). "Yet, it is imperative to examine the expression of FN3K in human breast cancer cells." (PMID 33466626, 2021). "In addition, the breast cancer cell death was substantially higher although the expression of FN3K enhanced with certain kinase inhibitors used for breast cancer treatment and the Nrf2 signalling was modulated consequently NQO1 and HO-1 antioxidant protein expression patterns also declined." (PMID 37910519, 2023). "However, the intricate functional aspects of FN3K and Nrf2 in breast cancers have not been explored vividly." (PMID 37910519, 2023). "Therefore, the development of small molecule inhibitors is a significant strategy to inhibit selectively FN3K in HCC, a strategy which may be used to target breast cancers." (PMID 37910519, 2023).
hepatocellular carcinoma (3 papers, 2020 to 2023). A malignant tumor that arises from hepatocytes. "FN3K is reported to be involved in deglycating the Nrf2 through phosphorylation of lysine, and arginine and enhancing Nrf2 activity in hepatocellular carcinoma, consequently protecting the cancer cells through antioxidant mechanisms." (PMID 37910519, 2023). "NSMIs targeting vulnerable FN3K could be an effective strategy to maintain Nrf2 in an inactive state; this was concluded from a genomic study in FN3K knockout mice models, where the data supported a specific need of FN3K for oncogenic Nrf2-driven lung and liver carcinomas." (PMID 33466626, 2021). "In hepatocellular carcinoma triggered by MYC and KEAP1 inactivation, fructosamine-3-kinase (FN3K), a kinase that triggers protein de-glycation, mediates NRF2 de-glycation that stabilizes NRF2 and executes its oncogenic function." (PMID 32640524, 2020).
lung carcinoma (3 papers, 2019 to 2025). "Recently, FN3K was identified as an important upstream regulator of the transcription factor NRF2, providing a proliferative advantage in liver and lung cancer cells." (PMID 39149269, 2024). "In the absence of Fructosamine-3-kinase, NRF2 is glycated and binds to the small MAF proteins and increases the transactivation of its target genes in liver and lung cancer cells." (PMID 31884422, 2019).
type 2 diabetes mellitus (3 papers, 2023 to 2025). A type of diabetes mellitus that is characterized by insulin resistance or desensitization and increased blood glucose levels. "Genome-wide association studies (GWAS) revealed a link between FN3K variants and elevating hemoglobin A1 (HbA1C) measurement and the onset of type 2 diabetes and its complications." (PMID 38162681, 2023).
cataract (2 papers, 2021 to 2023). Partial or complete opacity of the crystalline lens of one or both eyes that decreases visual acuity and eventually results in blindness. "A recent study investigating the effect of ex vivo intravitreal FN3K injections on AGE-based cataracts seems to be quite promising as a potential new treatment of certain types of cataracts." (PMID 36979358, 2023). "Our study suggests, for the first time, a potential additional role of FN3K as an alternative treatment for AGE-related cataracts." (PMID 33917258, 2021). "Only a subgroup of cataract patients are expected to benefit from the potential therapeutic effects of FN3K." (PMID 33917258, 2021). "Therefore, it is rather evident that FN3K treatment will not be able to provide an answer to all types of cataracts." (PMID 33917258, 2021).
ductal carcinomas (1 paper, 2023). "Our study reported the expression of FN3K in ductal carcinomas, which are invasive types." (PMID 37910519, 2023).
ductal invasive carcinoma (1 paper, 2023). "So, we have ascertained the IC-50 using cytotoxicity assays for these drugs and treated the invasive ductal breast carcinoma cells to examine the FN3K protein expression." (PMID 37910519, 2023). "FN3K expression in T47D cells: Furthermore, we have examined the FN3K expression patterns alone in the T47D, another ductal invasive carcinoma cell line." (PMID 37910519, 2023). "Expression of FN3K was significantly higher in ductal invasive carcinomas such as BT 474, T47D, and MCF-7." (PMID 37910519, 2023).
Erythema (1 paper, 2023). Redness of the skin, caused by hyperemia of the capillaries in the lower layers of the skin. "The effects of FN3K and FAOD on skin color, including erythema and pigmentation factors, in both anti-aging and scar improvement settings, should be the subject of future research." (PMID 37240327, 2023).
glioblastoma multiforme (1 paper, 2019). "Based on BLAST, such two peptides have be accurately realigned to two specific proteins, namely, transmembrane protein 39B and fructosamine-3-kinase, contributing to the identification of glioblastoma multiforme patients." (PMID 31850330, 2019).
presbyopia (1 paper, 2024). The normal decreasing elasticity of the crystalline lens that leads to loss of accommodation. "Based upon the published results of fructosamine 3-kinase (FN3K) and FAOD obtained in cataract and presbyopia, we studied ex vivo FAOD treatment as a non-invasive AMD therapy." (PMID 38732004, 2024).
cancer (8 papers, 2014 to 2025). A tumor composed of atypical neoplastic, often pleomorphic cells that invade other tissues. "A recent study uncovered the link between NRF2 glycation and FN3K dependency in cancer and identified FN3K as a potent NRF2 activator in malignancies." (PMID 39149269, 2024). "It has been observed that the substantial expression of FN3K can result in the deglycation of Nrf2 resulting in the overexpression of AREs to enhance the cancer cell antioxidant potential." (PMID 37910519, 2023). "Substantial studies are required to examine the activity of Nrf2 inhibitors/semisynthetic camptothecin derivatives like irinotecan, and topotecan along with FN3K inhibitors (oxaliplatin) in combinatorial regimens to target several cancers." (PMID 37910519, 2023). "Going forward, FN3K inhibition emerges as a new strategy to attenuate NRF2 functions in cancer that include broad resistance to different treatment modalities." (PMID 33562682, 2021). "Studies have demonstrated the key role of FN3K in the glycation of proteins and accumulation of AGEs in several cancers." (PMID 33466626, 2021). "The generation of glycated proteomes inside cancer cells solely depends on the glycatibility of a spatial or chemical nature of basic amino acids of proteins like Nrf2 and their sensitivity to FN3K-mediated deglycation." (PMID 33466626, 2021). "Together, our findings implicate NRF2 in the translation of eIF4A-dependent mRNAs and point to FN3K inhibition as a new strategy to block NRF2 functions in cancer." (PMID 33562682, 2021). "Further, we have highlighted the functional role of deglycating enzyme fructosamine-3-kinase (FN3K) on Nrf2-driven cancers." (PMID 33466626, 2021). "In this scenario, it is imperative to uncover the regulatory mechanism for the redox-active switch/feedback regulation of FN3K in deglycating Nrf2 in cancer cells." (PMID 33466626, 2021). "The deglycation of Nrf2 is catalyzed by FN3K, whose activity is enhanced during the progression of cancer cells into malignant and drug-resistant phenotypes." (PMID 33466626, 2021). "Accordingly, loss of FN3K results in NRF2 hyper-glycation and inactivation and resensitizes cancer cells to eIF4A inhibition." (PMID 33562682, 2021). "The authors of this novel study reported a pivotal role for FN3K in regulating Nrf2 activity during cancer progression." (PMID 33466626, 2021). "They proposed the mean degree of FN3K mRNA was very lower in cancer against equivalent typical colorectal mucosa." (PMID 35223406, 2021). "Functionally active FN3K makes oncogenic Nrf2 inactive by retaining it in a glycated state, suggesting the intricate and versatile role of FN3K in cancers." (PMID 33466626, 2021). "The high-throughput screening (HTS) of several novel conventional small molecule inhibitors and phytochemicals targeting FN3K is highly significant and contributes to the development of novel inhibitors for targeting oncogenic Nrf2-driven cancers." (PMID 33466626, 2021). "The activity of these molecules also should be examined against the FN3K-mediated deglycation of Nrf2 in several cancers." (PMID 33466626, 2021). "This kind of feedback inhibition is a regulatory mechanism of FN3K essential for the delgycation of proteins inside cancer cells/normal cells during oxidative stress." (PMID 33466626, 2021). "In this context, future research should focus on the development of therapeutic modalities targeting FN3K in Nrf2-driven cancers using molecular docking models in in vitro, in vivo, and clinical studies." (PMID 33466626, 2021). "Inhibitors of FN3K are being explored currently to modulate Nrf2 activity thereby control the cancers." (PMID 33466626, 2021). "It is currently unclear what mechanistic role FN3K plays in modulating NRF2 function in cancer." (PMID 39843453, 2025). "It is currently unclear what mechanistic role FN3K plays in modulating NRF2 functions in cancers." (PMID 39149269, 2024).
cancer (continued). "Therefore, the development of small molecule inhibitors is a significant approach to selectively block FN3K in cancers." (PMID 37910519, 2023). "FN3K is a deglycating enzyme reported to induce deglycation of Nrf2 which results in the activation of antioxidant responses to regulate oxidative stress to offer cancer cell protection." (PMID 37910519, 2023). "A previous study depicted the knockdown of FN3K could induce a higher glycated Nrf2 in the cancer cells." (PMID 37910519, 2023). "The catalytic activity of the FN3K deglycating enzyme has a significant role in cancer cells to modulate the oncogenic activity of Nrf2, as the blockade of FN3K could induce glycated Nrf2 to remain Nrf2 in an inactive state." (PMID 33466626, 2021). "However, the current research reporting on the deglycation of Nrf2 requires extensive research not only to determine the role of FN3K in cancers but, also, to develop novel pharmacological agents to modulate the expression of glycated Nrf2 in cancers." (PMID 33466626, 2021). "FN3K is a proven drug target to mitigate Nrf2-driven cancers." (PMID 33466626, 2021). "However, Nrf2 protein deglycation in cancers is mediated by FN3K, concluding that the activity of Nrf2 needs FN3K." (PMID 33466626, 2021). "Hence, novel therapeutic agents to modulate the enzymatic activity of FN3K are imperative for individual cancers by determining the specific role of FN3K for every cancer." (PMID 33466626, 2021). "Hence, deglycation pathways mediated by FN3K have plausible significance in certain cancers, such as colorectal carcinomas." (PMID 33466626, 2021). "The FN3K-sensitive glycation of several hepatic proteins, such as translation factors, DNA replication and repair proteins, splicing factors, and histone proteins, has been reported in several cancers." (PMID 33466626, 2021). "Therefore, targeting Trp219 in FN3K might provide a specific handle to regulate FN3K-mediated phosphorylation in cancer cells and other pathological conditions." (PMID 39149269, 2024). "The lack of positive selection for a hyperactive FN3K variant might suggest deleterious effects that outweigh survival benefits in cancer cells." (PMID 39149269, 2024). "FN3K may represent a novel target of Nrf2 activity in cancer." (PMID 35335911, 2022). "In this context, the development novel FN3K inhibitors in combination with current chemotherapeutic molecules as nanoformulations may deliver selectivity and specificity in promoting the formation of glycated Nrf2 for treating several Nrf2-mediated cancers." (PMID 33466626, 2021). "However, the global inhibition of deglycation has yet to be extensively reported in all other cancer types with selectivity and tissue specificity to develop novel FN3K inhibitors to maintain Nrf2 in a glycated state or to modulate the role of Nrf2 activity in cancers." (PMID 33466626, 2021). "FN3K-mediated deglycation of Nrf2 could confer cancer progression in HCC." (PMID 33466626, 2021). "Further analysis showed that FN3K knockdown resensitized human NSCLC lines (H3255 and PC9) to erlotinib treatment, highlighting the therapeutic potential of targeting FN3K in cancer cells that exhibit survival dependency on NRF2." (PMID 39149269, 2024). "Fructosamine-3-kinase (FN3K) is involved in the deglycation of Nrf2, a significant regulator of oxidative stress in cancer cells." (PMID 37910519, 2023). "However, the application of genomics/transcriptomics/proteomics-centric approaches as multi-OMICS strategies may deliver key insights into the complex role of FN3K in several individual cancers to develop gene-based therapies to modulate the expression of FN3K." (PMID 33466626, 2021). "As a result of these unfavorable impacts, cancer cells depend on the outflow of aldehyde barrier proteins, for example, GLO1 to evade extreme aldehyde stress and FN3K to confine AGE-amassing." (PMID 35223406, 2021).
cancer (continued). "FN3K could enhance the deglycation of Nrf2 consequently increasing the antioxidant role of Nrf2 in HCC, and offering protection for cancer cells during chemotherapy." (PMID 37910519, 2023). "The differential expression of FN3K in cancer cells rather than normal cells has significant implications in the pathophysiology of several cancers." (PMID 33466626, 2021).
tumor (5 papers, 2014 to 2023). "The current study demonstrated that oxaliplatin significantly downregulated the FN3K protein expression, a deglycating enzyme involved in Nrf2 glycation, a process implicated in tumor progression." (PMID 37910519, 2023). "Whereas the mRNAs of genes that helps in tumor inhibition like Galr1, tumor suppressor Gnmt and Fn3k were significantly increased." (PMID 26429877, 2015). "FN3K was upregulated in the tumor class in the CMS data, and in WNiCo alone with a fold change of 1.7 times greater in WNiCo than in Ta." (PMID 24619124, 2014). "Hence, future studies should develop strategies to target FN3K either alone or in combination with Nrf2 for effective tumor retardation." (PMID 33466626, 2021).
FN3K also shares sentences with these, for which no sentence is quoted: macular degeneration (2 papers); adenoma (1); age-related macular degeneration (1); arterial hypertension (1); colon cancer (1); colorectal cancer (1); type 1 diabetes (1).